IL6 (interleukin 6)
Diseases named in the same sentence as IL6 in open-access papers (continued):
Sharing a sentence is not in itself a finding about the gene and the disease.
breast cancer (continued). "Increased concentrations of inflammatory cytokines such as interleukin-6 (IL-6) and tumor necrosis factor-α (TNF-α) in breast cancer patients promote tumor progression, angiogenesis, and invasion." (PMID 40720508, 2025). "Interleukin-6 (IL-6) induces an epithelial-mesenchymal transition (EMT) phenotype in human breast cancer cells, and direct application of IL-6 to breast cancer cells increases proliferation in estrogen receptor-positive (ER+) cells." (PMID 40043049, 2025). "Among the human breast cancer cell line (MCF-7), human dermal fibroblasts (NHDF), and human ADSCs, ADSCs showed the highest expression of IL-6 by quantitative PCR." (PMID 40211386, 2025). "This systematic review highlights consistent associations between increased pro-inflammatory cytokines (i.e., IL-6, IL-1β, TNF-α), reduced levels of hippocampal BDNF, and cognitive impairment in preclinical models of breast cancer and chemotherapy." (PMID 41155372, 2025). "As a result of IL-6 and SNAI1 upregulation, compressed breast cancer cells exhibit a more aggressive metastatic phenotype and are more likely to undergo migration and invasion to distal sites." (PMID 40371393, 2025). "AE directly modulates the inflammatory milieu by reducing the levels of key pro-inflammatory cytokines such as TNF-α, IL-6, and CRP, as evidenced in breast cancer studies." (PMID 41480347, 2025). "Roubert et al177 demonstrated a positive correlation between BMI and the secretion of IL-1, IL-6, and TNF-α, which promote breast cancer by stimulating wingless/integrated (Wnt) signaling in mammary tissue." (PMID 40584290, 2025). "Several human studies also support this inflammation–angiogenesis axis, reporting positive correlations between IL-6 or TNF-α and circulating VEGF levels in patients with breast cancer, small cell lung cancer, and melanoma." (PMID 41583457, 2025). "For example, IL-6 is highly expressed in this microenvironment and can activate the STAT3 pathway through paracrine and autocrine pathways, thereby promoting breast cancer cell proliferation." (PMID 40860340, 2025). "Another report showed that IL-6 induces STAT3-mediated miR-21 activation, and functions as an epigenetic switch in breast cancer." (PMID 40843360, 2025). "CM with high IL-6 levels induces PD-L1 expression through the STAT3 and AKT pathways, and breast cancer cells treated with high IL-6 CM exhibit resistance to chimeric antigen receptor T-cell (CAR-T) cell killing." (PMID 40890855, 2025). "The aim of this study was to evaluate the prognostic relevance of serum IL-6 and TNF-alpha levels on survival and treatment response in women with breast cancer." (PMID 40558287, 2025). "The effect of IL-6 on cancer has long been recognised, with evidence showing that it induces higher proliferation and EMT changes in ovary cancers, breast cancers, and HNSCC, as well as promoting an immunosuppressive TME." (PMID 39858048, 2025). "Our findings demonstrate a significant upregulation of key pro-inflammatory cytokines such as IL-6, IL-1β, TNF-α, and IL-12 (p40) in the plasma of breast cancer patients, with expression correlating positively with tumor stage and grade." (PMID 40612845, 2025). "IL-6, by increasing JAK2-STAT3 pathway activation, promotes the proliferation and invasion of breast cancer cells." (PMID 40034598, 2025). "Breast cancer cells can directly stimulate osteoclastogenesis by secreting factors such as receptor activator of nuclear factor kappa-Β ligand (RANKL), IL-1, IL-6, and tumor necrosis factor-alpha (TNF-α)." (PMID 40444046, 2025). "For example, in breast cancer, elevated expression of DNMT1 is observed in M2 macrophages via the IL-6-pSTAT3-ZEB1-DNMT1 axis." (PMID 40380196, 2025). "In breast cancer, KYNA binds to AhR to promote IL‐6 expression (enhanced binding of AhR with RelB leads to increased IL‐6 transcription)." (PMID 40103267, 2025).
breast cancer (continued). "Rosuvastatin, in randomized controlled trial, has been shown to reduce the levels of interleukin (IL)-6 and high-sensitivity cardiac troponin I (hs-cTnI) in 50 newly diagnosed HER2-positive breast cancer patients and chemotherapy-treated patients." (PMID 41302173, 2025). "In this study, we identified circRNA-14,052 as a novel oncogenic circRNA that promotes breast cancer progression by sponging miR-214-3p and upregulating IKBKB, thereby activating the IL-6/JAK2/STAT3 signaling axis." (PMID 41044672, 2025). "SDC1 relies on the IL-6/STAT3, Notch and EGFR pathways to induce stem cell formation in breast cancer, Ibrahim et.al." (PMID 41364407, 2025). "A recent study also highlighted the importance of STAT3 signaling activated by TAM-derived IL-6 in CSC enrichment and tumor growth in breast cancer." (PMID 40083697, 2025). "This methodology has been effective in uncovering optimal drug targets in various contexts, including previously established targets for breast cancer (e.g., SRC, MTOR) and spinal cord injury (e.g., TNF, FOS, IL6)." (PMID 40895536, 2025). "Breast cancer cells enhance tumor survival by HER2 signaling, while astrocyte-derived STAT3 and cytokines such as interleukin-6 (IL-6) and interferon-alpha (IFNα) protect tumor cells from apoptosis." (PMID 41429896, 2025). "In breast cancer, it decreases tumor necrosis factor-α (TNF-α), interleukin-6 (IL-6), and CRP while enhancing metabolism and immunity." (PMID 41280723, 2025). "It was discovered that MCF-7 breast cancer cell production of vimentin, SNAIL-2/SlugZEB-1, and SNAIL-1 was increased by IL-6 in senescence-conditioned medium from senescent foreskin fibroblasts, hydroxycarboxylic acid receptor 2 (HCA2)." (PMID 40584290, 2025). "In contrast, the TNBC subgroup showed a markedly heightened expression of IL-6 and MCP-1, both at the gene and protein levels, reinforcing their potential as biomarkers for aggressive breast cancer phenotypes." (PMID 40612845, 2025). "An article reported that the levels of IL-6 and TNF-α in the serum of breast cancer patients lowered vitally after AE, determining that AE can positively modulate the levels of these pro-inflammatory factors." (PMID 41480347, 2025). "TNF-α and IL-6 promote inflammation in the TME, facilitating breast cancer cell proliferation and metastasis." (PMID 41289612, 2025). "The study examined the regulation of PD-1, PD-L1, MMP-9, AGEs, AOPPs, IL-6, 8-OHdG and TNF-α expression in a rat model of breast cancer induced by DMBA." (PMID 40008130, 2025). "Herein, we demonstrated reduced expression of IL-6 and IL-8 in response to LDHB KO or LDH inhibition in ER- breast cancer cells." (PMID 40507273, 2025). "When 164 breast cancer patient samples were tested when they were menopausal, researchers discovered a favorable link between the expression of TNF-α and IL-6 and breast cancer cells." (PMID 40584290, 2025). "For example, in breast cancer, STAT3 is frequently activated by interleukin-6 (IL-6) through the Janus kinase (JAK) pathway, promoting an inflammatory microenvironment that fosters tumor growth." (PMID 40075607, 2025). "TAM-derived IL-6 plays a crucial role in TAM-mediated cancer stem cell enrichment by activating STAT-3 signalling and influencing breast cancer cell migration and angiogenesis; however, its expression was relatively low across all groups." (PMID 40547518, 2025). "The IL6/JAK/STAT3 signaling pathway is a classical pathway that influences the onset and progression of breast cancer." (PMID 40841364, 2025). "Recent studies have identified iCAF in several tumour types, including pancreatic cancer and breast cancer, using a variety of markers that encompass inflammatory cytokines and other genes (CXCL1, CXCL8, CXCL12, IL6, CFD, DPT)." (PMID 39757146, 2025).
breast cancer (continued). "In another study, increased levels of IL-6 and IFN-γ were measured in the serum of mistletoe-treated breast cancer patients." (PMID 40369535, 2025). "Elevation of IL6 expression levels observed in THP1 cells and PBMCs exposed to breast cancer cells further supports the involvement of cytokine-mediated signaling in this reprogramming process." (PMID 41514627, 2025). "Namely, mice with melanoma tumors demonstrated higher levels of CXCL10, IL-6, and CCL2 in the serum compared to mice with control breast carcinoma tumors." (PMID 39857957, 2025). "Mras, Met, Rantes, IL6, and IL8 are targets of uSTAT3 after stimulation of the cells with IL6, and for breast cancer and head and neck squamous cell carcinoma cyclinB1 and E2f1 were also described as targets of uSTAT3." (PMID 38705997, 2024). "Recent studies have demonstrated that the release of cytokines, including G-CSF, IL-6, and TGF-β by breast cancer cells influences the expansion and activation of MDSCs, establishing a link between MDSCs and breast cancer progression." (PMID 38779867, 2024). "Numerous studies have shown that the UPR can promote the proliferation of tumors such as liver cancer, melanoma, and breast cancer through various signaling cascades such as IRE1/XBP1/JNK, IRE1/XBP1/IL-6/STAT3, and IRE1/TRAF2/NF-κB." (PMID 39080273, 2024). "IC50 concentrations were given to breast cancer co-culture models (MCF-7/THP-1 and MDA-MB-231/THP-1) planted and merged according to the procedure, and after 24 h using flow cytometry, IL-1β, IL-6 levels of IL-8, IL-10, and TNF-α were measured." (PMID 39175950, 2024). "DiMeOC-Mg-BCD decreased the expression of metalloproteins, IL-6, and STAT3 in the MDA-MB-231 breast cancer cell line, leading to the induction of apoptosis." (PMID 38673967, 2024). "Another recent report indicates that IL-6 is a target of YAP and plays an important role in maintaining the stemness of breast cancer cells." (PMID 37950040, 2024). "In a model of desmoplastic reactions consisting of breast cancer cells cocultured with fibroblasts, melatonin reduces the levels of TNF-α, IL-6 and IL-11 mRNA expression." (PMID 38473317, 2024). "In the present study, we exposed breast cancer cells to the ELIT cocktail (17β-estradiol, leptin, IL6, and TNFα) simulating the hormonal and inflammatory conditions of postmenopausal obesity." (PMID 39767718, 2024). "IL-6, stimulated through STAT3, fosters malignant properties, expanding the breast cancer stem cell population." (PMID 38347830, 2024). "Tumor-educated Gr1+CD11b+ cells convert low metastatic SCA1- breast cancer cells into highly metastatic SCA1+ cells via secreted OSM and IL6 and JAK signaling." (PMID 38236642, 2024). "This indicates that breast cancer cells can downregulate DCN and activate NBFs in an IL-6-dependent manner, through the activation of STAT3/NF-κB signaling." (PMID 38667295, 2024). "The effects of Apigenin on EMT were evaluated in vitro and in vivo using highly metastatic breast cancer cells (MDA-MB-231 cell line) that endogenously expressed the pro-EMT, interleukin-6 (IL-6)." (PMID 38791608, 2024). "Breast cancer patients with low ARID1A expression, who have received radiotherapy (RT) demonstrated higher IL-6 expression compared to patients with high ARID1A expression." (PMID 38587186, 2024). "Inflammatory cytokines IL-6, IL-8, and TGF-β1 induce proliferation from dormant breast cancer cells." (PMID 38457510, 2024). "Within breast cancer stem cells, the HMGB1/TLR2/MyD88 axis governs NF-κB activation, IL-6 and TGF-β production, and the activation of STAT3 and Smad3." (PMID 38347830, 2024). "Both primary and lymph node metastasis (N1-N3) of breast cancers promoted MCT-1, PD-L1 and IL-6 expression, while MCT-1 and IL-6 were upregulated in another distant metastasis (M1), supporting their metastatic roles." (PMID 38505617, 2024).
breast cancer (continued). "Recent literature indicates that PRMT6 promotes breast cancer migration and distant metastasis by methylating STAT3, thereby regulating the IL-6/STAT3 pathway." (PMID 38637831, 2024). "Cytotoxic stress from infiltrating lymphocytes stimulates breast cancer cells to produce CCL5, which activates CCR5 signaling and mobilizes TAMs, and TAM-derived factors (OPN, HB-EGF, and IL-6) stimulate breast cancer cell growth." (PMID 39199574, 2024). "Collectively, our results demonstrate that tGLI1 and IL-6 signaling pathways are frequently co-overexpressed, co-enriched, and co-activated in HER2-enriched breast cancers and TNBCs." (PMID 39768178, 2024). "Breast cancer tumorspheres presented a statistically significant increase in CXCL8, IL6, IL6R, and NFKB1 mRNA levels in comparison to adherent cell culture, while TGFB1 mRNA expression was decreased." (PMID 39336151, 2024). "Inhibition of the PI3K/AKT/mTOR axis has been shown to elicit senescence in breast cancer, resulting in the secretion of SASP factors (CCL2, CXCL1, CXCL8, IL‐6), which induce an M2‐like polarisation." (PMID 39270064, 2024). "Elucidation of the mechanisms underlying the anticachectic effect of MPA showed that the secretion of IL-6 from the KPL-4 cell line, the first cell line of human breast cancer, induces cachexia." (PMID 38956273, 2024). "tGLI1+IL-6/IL-6R/GP130 signaling is frequently co-enriched and co-activated in HER2-enriched breast cancer and TNBC when compared to luminal subtypes." (PMID 39768178, 2024). "We also show that whereas the upregulation of MRP1 and MDR1 is a direct target of NF-κB activity as reported by others in breast cancer, the upregulation of BCL-xL is an indirect target via the autocrine IL-6/STAT3 loop as reported in liver cirrhosis." (PMID 38806726, 2024). "In breast cancer, CEBPD reportedly links to interleukin-6 and hypoxia-inducible factor 1 signaling to promote cancer stem cell-associated phenotypes, which is a well-known factor correlated with drug resistance." (PMID 38627816, 2024). "IL-6 stimulates miR-155 expression which is known to target suppressors of cytokine signalling pathway (SOCS), hence promoting the progression of breast cancer." (PMID 38726321, 2024). "In conclusion, the expression of IL6 and IL8 was significantly increased in TAM-R cells, and FOXA1 affected the endocrine resistance of breast cancer by targeting the downstream factor IL6/8." (PMID 38605023, 2024). "Co-overexpression of IL-6 and phosphorylated STAT3 (pSTAT3) is commonly observed in breast cancer and other cancer types." (PMID 39451730, 2024). "In this study, we identified tGLI1 and IL-6/IL-6R/GP130 signaling pathways to be frequently co-overexpressed, co-activated, and functionally cooperate to promote breast CSCs in HER2-enriched breast cancer and TNBC." (PMID 39768178, 2024). "Isolation of stromal fibroblasts from breast cancer tissue and analysis of the supernatant showed that IL-6 downregulated the tumor suppressor HIC1 and promoted the development of breast cancer in the TME through paracrine or autocrine signals." (PMID 37978384, 2023). "In addition, we previously noted that TrkB activates the IL6/JAK2/STAT3 signaling pathway in breast cancer via the formation of the TrkB/JAK2 complex and then induces the EMT program by upregulating Twist-1, suggesting that DJ-1 and TrkB may orchestrate to activate the STAT3 signaling pathway." (PMID 37749450, 2023). "As a proof of principle, we investigated the mechanism of action of soluble factors involved in breast cancer progression, such as TGF-β, PDGF, and IL-6." (PMID 37173963, 2023).
breast cancer (continued). "We propose that this is due to the secretion of multiple cytokines that have been shown to increase breast cancer aggressiveness, namely CXCL5, COX-2, MMP-9, and IL-6." (PMID 37760470, 2023). "In this study, it was aimed to evaluate the roles of CAFs-derived IL-6 in doxorubicin (Dox) resistance and PD-L1-mediated chimeric antigenic receptor (CAR)-T cell resistance in breast cancer (BCA)." (PMID 37480115, 2023). "IL-6-induced p-STAT1 and p-STAT3 were lower in naïve CD4+ T cells from breast cancer patients compared to healthy donors." (PMID 37741983, 2023). "Inflammatory cytokines, such as IL-6 and TNF-α, have been found to upregulate ANXA1 expression in breast cancer cells." (PMID 37507468, 2023). "The continuous activation of the IL-6/STAT3 signaling pathway has been detected in cell proliferation, survival, and invasion of many human cancers, including breast cancer." (PMID 37298475, 2023). "To determine the degree to which the breast cancer cell lines MCF-7 and MDA-MB-231 responded to the LPS treatment, we treated these cells with LPS and measured the expressions of the COX-2 and IL-6 genes in both cell lines." (PMID 37371732, 2023). "GWAS that implicate BNC2-associated alleles with adolescent idiopathic scoliosis also implicate other ECM-associated genes and cytokines that we also find to be under BNC2 control in our breast cancer system (MATN1, MMP9, SOX9, IL-6 as examples)." (PMID 37536977, 2023). "The ability of HDL to inhibit IL6 and TNF production was higher in breast cancer compared to controls, especially in advanced stages of the disease." (PMID 37628945, 2023). "Collado-Hidalgo’s team conducted research on the dependence between markers of fatigue and inflammation, and their results showed increased production of interleukin IL-6 and TNF-α in breast cancer survivors with symptoms of fatigue." (PMID 36834426, 2023). "Furthermore, using a syngeneic mouse model of breast cancer dormancy, both orthotopic and metastatic, we confirmed the deleterious effects of taxane-based chemotherapy in dormancy awakening in vivo, and systemic release of proinflammatory cytokines IL-6 and G-CSF." (PMID 37699010, 2023). "Exosomal miR‐183 derived from breast cancer cells elevates the levels of TNF‐α, IL‐6, and IL‐1β in macrophages." (PMID 36705422, 2023). "Disseminated breast cancer cells that migrate to the bone release several factors, such as PTHrP, TGF-β, and IL-6, that perturb the normal bone-remodeling process to create a microenvironment that facilitates tumor engraftment in the bone." (PMID 36692956, 2023). "They measured the serum levels of P1NP, CTX, IL-6, and osteocalcin in the blood of 164 pre-treatment stage I-III breast cancer patients to explore the relationship between these markers and bone metastasis and overall survival." (PMID 38041134, 2023). "Recombinant IL-6 significantly enhanced the level of p-STAT3 and resulted in increased clone numbers of breast cancer cells in a concentration dependent manner." (PMID 36635302, 2023). "For instance, several studies have demonstrated a noteworthy elevation in the concentrations of IL-5, IL-6, IL-7, and TNF-α in both the pathological tissue and systemic circulation of breast cancer patients, as compared to healthy individuals." (PMID 37910571, 2023). "Autocrine IL-6 signaling, which proceeds via the JAK/STAT3 pathway, is known to promote breast cancer proliferation, survival, migration, and invasiveness." (PMID 38250802, 2023). "However, the function of CAF-derived IL-6 in breast cancer cell radiosensitivity is unknown." (PMID 36635302, 2023). "In particular, inhibition of the adipokine IL-6 by GREM2 had an effect in suppressing proliferation, migration, and metastasis of breast cancer cells in the breast cancer microenvironment." (PMID 37880751, 2023). "Previous studies have shown that IL-6 plays an essential role in regulating the self-renewal of stem cells and TRZ resistance in HER2+ breast cancer." (PMID 36979654, 2023).